REN (renin)
Diseases named in the same sentence as REN in open-access papers (continued):
Sharing a sentence is not in itself a finding about the gene and the disease.
Hypertension (continued). "The pathophysiology of hypertension in relation to SAS is dependent on various factors; for example, the sympathetic tone, peripheral vasoconstriction, altered baroreceptor reflexes, increased renin–angiotensin system activity, and increased plasma noradrenaline concentrations." (PMID 35682548, 2022). "This suggests that the postponed development of high blood pressure in PC-H fed rats could be regulated through the renin-angiotensin system; however, since ACE and renin activities are measured in vitro these may not be directly transferable to effects in the rats." (PMID 30469459, 2018). "Perturbations in the renin-angiotensin-aldosterone system (RAAS) and nitric oxide (NO) pathway in immune cells and in the endothelium can contribute to the development of hypertension, but how these pathways influence disparities in hypertension etiology is not clear." (PMID 28660007, 2017). "Alteration in transcriptional environment of the kidney or epigenetic change in proximal promoter region of renin genes by long-term exposure to high concentration of AII and/or high blood pressure, in combination with a lack of distal sequences may account for the phenotype." (PMID 27861631, 2016).
diabetes (541 papers, 2004 to 2026). "The underlying cause of hyporeninemia is thought to be either a defect in the conversion of the precursor prorenin to its active form renin or the suppression of renin secretion due to diabetes-associated fluid overload." (PMID 40498214, 2025). "The presence of diabetes in the context of hyperglycemia increases insulin resistance and causes endothelial dysfunction with the activation of the renin–angiotensin system and levels of AG II." (PMID 39062156, 2024). "It is a transgenic rat with the additional renin gene that develops diabetic nephropathy, whereas exposure to streptozocin causes diabetes in these rats." (PMID 39337409, 2024). "Diabetes is a well-known cause of hyporeninism-hypoaldosteronism because of defective conversion of prorenin to renin." (PMID 38434606, 2024). "Pro-inflammatory cytokines and chemokines, as well as increased renin-angiotensin-aldosterone system activity in diabetes have also been implicated in the development of myocardial fibrosis." (PMID 38443793, 2024). "Low ANP levels are associated with the development of diabetes and insulin resistance through the activation of the renin–angiotensin system." (PMID 37240345, 2023). "CKD patients, especially those with associated Diabetes Mellitus (DM), are more susceptible to present with K+ disorders, in particular HK due to kidney disease progression or use of renin-angiotensin-aldosterone blockers." (PMID 37583425, 2023). "It was linked to diabetes-associated hypertension, as elevated succinate in diabetes stimulates renin production via GPR91." (PMID 37446354, 2023). "Sex and the pulse pressure in male subjects were found to be independently associated with renin while disease (diabetes or obesity), age, height z-score, glomerular filtration and MAP were not." (PMID 36996194, 2023). "Plausible explanations are the predisposition of elderly women with diabetes to develop HF, and especially HFpEF, more often than men, together with the presence of an overly activated renin–angiotensin–aldosterone system in response to low oestrogen levels." (PMID 36347992, 2023). "The contribution of genetic polymorphisms of the entire intra-renal renin-angiotensin-aldosterone system in the pathogenesis of diabetes and diabetic nephropathy is provided by extensive clinical and experimental data." (PMID 35176079, 2022). "Possible pathogenetic mechanisms underlying diabetes and COVID-19 disease are deteriorated immune function, inflammation and glucotoxicity, activation of renin-angiotensin-aldosterone system, and endothelial damage." (PMID 36061633, 2022). "More convincingly, in patients with diabetes, a decreased risk of COVID‐19 requiring hospitalization was observed in users of renin‐angiotensin‐aldosterone system inhibitors." (PMID 33210392, 2021). "We found that diabetes was associated with cardiac muscle injury by activating the renin-angiotensin-aldosterone system, myocardial inflammation, and fibrosis." (PMID 33240696, 2020). "Vitamin D deficiency is additionally linked to activation of the renin–angiotensin system, promoting endothelial damage and the progression of diabetes." (PMID 31126256, 2019). "In summary, drug-nephrotoxicity and diseases such as diabetes and other conditionsassociated with underproduction of renin or aldosterone are the main causes ofhyperkalemic RTA in clinical practice." (PMID 30048563, 2018). "Activation of the renin-angiotensin system is often associated with diabetes where it is thought to impact the initiation and progression of the disease." (PMID 30534081, 2018). "Patients with type 2 diabetes mellitus and albuminuria have higher risk of heart failure, and treatment directed at modulating the renin–angiotensin–aldosterone system (RAAS) decreases rate of hospitalization with cardiac decompensation." (PMID 28716801, 2017).
diabetes (continued). "Diabetes Mellitus is associated with severe cardiovascular disorders involving the renin-angiotensin system, mainly through activation of the angiotensin II type 1 receptor (AT1R)." (PMID 28361992, 2017). "None of three patients had other risk factor including complication of diabetes mellitus and concomitant use of renin-angiotensin inhibitor." (PMID 28378068, 2017). "Increased activity of the renin-angiotensin system is strongly associated with CKD and diabetes; vitamin D is a negative regulator of the renin-angiotensin system." (PMID 28754147, 2017). "The relief of microalbuminuria with the blockade of the renin-angiotensin-aldosterone system is known to be a key therapeutic strategy for reducing the risk of renal and cardiovascular events in patients with diabetes." (PMID 28033332, 2016). "Diabetes mellitus is a group of metabolic disorders resulting from hyperglycemia caused by genetic, molecular, or biochemical factors and activation of renin–angiotensin system (RAS), which eventually leads to the damage of end-organs like kidney." (PMID 26217336, 2015). "Adenosine plays an important role in water-electrolyte metabolism, such as retinal blood flow and renin release, which make the patients with diabetes be susceptible to retinopathy." (PMID 24688543, 2014). "Excess activity of the renin-angiotensin system is associated with high blood pressure, kidney disease and diabetes." (PMID 28197449, 2014). "Upregulation of the renin-angiotensin system (RAS) has been described in diabetes and is associated with the development of cardiac hypertrophy and fibrosis." (PMID 24223630, 2013). "Up-regulation of the renin-angiotensin system (RAS) has been described in diabetes and is associated with development of cardiac hypertrophy and fibrosis." (PMID 21798071, 2011). "This article discusses the clinical trial evidence for modalities associated with a reduction in the risk of new-onset diabetes, with a focus on the role of antihypertensive agents that block the renin–angiotensin system." (PMID 19220522, 2009). "Treatment with antihypertensives acting on the renin–angiotensin–aldosterone system (RAAS) has been associated with improved cognitive function in patients with diabetes in terms of executive abilities, processing speed and verbal memory compared to those treated with other antihypertensives." (PMID 39876043, 2025). "Our FinnGen-based results suggest that genetic liability to the use of agents acting on the renin–angiotensin system, diuretics, thyroid preparations, or diabetes drugs may be associated with melanoma risk." (PMID 41153759, 2025). "For example, SGLT2 inhibitors, commonly used in diabetes management, cause glycosuria and may alter urinary specific gravity, while renin-angiotensin-aldosterone inhibitors can decrease proteinuria." (PMID 39924305, 2025). "Vasculopathies due to dysfunctional regulation of the renin-angiotensin-aldosterone pathway have been linked to systemic vasculopathy in type 2 diabetes mellitus including nephropathy, coronary heart disease, cerebrovascular disease, peripheral arterial disease, and retinopathy." (PMID 39561140, 2024). "Calcium channel blockers, HMG CoA reductase inhibitors, agents acting on the renin-angiotensin system, antithrombotic agents, diuretics, beta blocking agents, salicylic acid and its derivatives, drugs used in diabetes, and vasodilators used in cardiac diseases were linked to an increased LAS risk." (PMID 37020515, 2023). "It has also been shown that SGLT2i may reduce cardiovascular (CV) risk in patients with type 2 diabetes mellitus (T2DM) by affecting the aldosterone/renin ratio (ARR) through diuretic and sympathetic depressant effects." (PMID 36589841, 2022). "For Pb, one hypothesis is that low-level environmental Pb exposure can lead to oxidative stress reactions causing functional nitric oxide deficiency and activation of the renin-angiotensin-aldosterone system in patients with diabetes." (PMID 32751456, 2020).
diabetes (continued). "Furthermore, inhibiting the renin enzymatic activity can improve periodontal bone loss and inflammatory response and exacerbate wound healing process, mainly in diabetes." (PMID 31333451, 2019). "A higher association of HDL, TG, Leptin & Renin was seen with having FH of diabetes in our study." (PMID 26430439, 2015). "Among the clinically important causes for elevated aldosterone level, primary hyperaldosteronism is the most common cause of secondary arterial hypertension, and type 1 diabetes mellitus causes inappropriate activation of the entire renin-angiotensin-aldosterone axis." (PMID 25000288, 2014). "Additionally, in patients with evidence of renal disease or at greater risk of developing renal disease, such as those with diabetes mellitus, it is recommended to use renin-angiotensin-aldosterone system blocker–based combination therapy." (PMID 23110471, 2012). "The study was designed to evaluate whether reducing postprandial hyperglycaemia and blockade of the renin-angiotensin-aldosterone system or both interventions reduce the risk of diabetes and cardiovascular events in patients with IGT." (PMID 22741568, 2012). "Traditional CV risk factors such as HTN, DL, and diabetes mellitus (DM) along with high concentrations of biomarkers associated with inflammation, fibrosis, congestion, and renin-angiotensin-aldosterone system activation all lead to a higher risk of HF." (PMID 36632250, 2022). "Thus, considering that SARS-CoV-2 binds to ACE2 and enters infected cells, reducing the ACE2 expression, overactivation of the renin-angiotensin system may also increase the risk of adverse events in patients with COVID-19 and diabetes." (PMID 33332437, 2020). "Plasma renin and atherosclerosis are concomitantly increased in subjects with T2D as compared to age and sex-matched subjects without T2D suggesting that these associations may be of particular importance in vascular complication of diabetes." (PMID 27596252, 2016). "Despite recognized benefits of renin–angiotensin–aldosterone system blockade in individuals with diabetes, a greater reduction in dietary sodium intake is associated with an increased risk of developing aldosterone escape, which may be associated with increased cardiovascular and renal morbidity." (PMID 28066329, 2016). "Indeed, experimental data supports the notion that low ANP levels predisposes to development of diabetes and insulin resistance through an activation of the renin-angiotensin system, and direct beneficial effects of ANP on the beta-cell have also been reported." (PMID 24586593, 2014). "Treatment with renin–angiotensin–system inhibitors and statins, when indicated, were 72.8% and 32.2%, respectively, and more frequent in individuals with diabetes." (PMID 40900939, 2025). "SUCNR1’s expression extends to tubular cells, which are the predominant producers of (pro)renin in individuals with diabetes." (PMID 38182909, 2024). "In a specialty diabetes-endocrinology clinic, the aldosterone:renin ratio (ARR) was assessed in 115 consecutive RH patients (ages 21-93 years; 47% male; 87% with type 2 diabetes)." (PMID 39445045, 2024). "During diabetes, the intrarenal renin–angiotensin system (RAS) is inappropriately activated as reflected in the stimulation of intrarenal renin and prorenin synthesis, angiotensin-converting enzyme (ACE), and intratubular levels of angiotensinogen (AGT)." (PMID 38203807, 2024). "Recent work has also highlighted the interaction between iron, SUCNR1 and the renin–angiotensin system in diabetes-related neurodegeneration and vascular abnormalities, stressing the role of iron homeostasis in preventing retinal oxidative stress." (PMID 38182909, 2024). "Other situations such as catecholamine increase or the use of diuretics or estrogens can increase renin, while age, diabetes, and chronic kidney diseases can decrease renin." (PMID 39416427, 2024).
diabetes (continued). "We assessed clinical and pathological attributes, including the Charlson comorbidity index, the prevalence of diabetes, renal function, and treatment with renin-angiotensin-system inhibitors (RASIs)." (PMID 38399535, 2024). "The imbalance of renin-angiotensin-aldosterone system (RAAS) is a characteristic of ADCHF combined with diabetes." (PMID 38582861, 2024). "Initially, during the early stages of diabetes, compensatory hyperinsulinemia stimulates sympathetic nerves and boosts renin secretion, resulting in elevated blood pressure." (PMID 38954387, 2024). "Persons with diabetes and chronic kidney disease (CKD) have a high residual risk of developing cardiovascular (CV) complications despite treatment with renin-angiotensin system blockers and sodium-glucose cotransporter type 2 inhibitors." (PMID 36719097, 2023). "Available data suggest inhibition of the pancreatic local-renin-angiotensin system (RAS) reduces tissue complications of diabetes." (PMID 36647426, 2023). "In the subgroup analysis, excluding patients treated with beta-blockers, renin-angiotensin inhibitors and/or having diabetes mellitus, autonomic dysfunction was still highly prevalent." (PMID 36650504, 2023). "At 15 weeks of diabetes, immediately prior to the treatment period, plasma renin was unchanged, prorenin had quadrupled to 1948 ± 179 ng angiotensin I per ml·h−1, and plasma angiotensinogen was reduced to 322 ± 22 pmol·ml−1." (PMID 36106615, 2023). "In contrast to male rodent models of obesity and diabetes, females are protected from metabolic and cardiovascular derangements produced by angiotensinogen, renin, and angiotensin II." (PMID 37049573, 2023). "The renin-angiotensin system and its metabolites are crucial in the pathogenesis and progression of complications of diabetes." (PMID 38098900, 2023). "Periodontitis patients purchased significantly more drugs used in diabetes (p = 0.035), calcium channel blockers (p = 0.016), drugs acting on the renin-angiotensin system (p = 0.024), and nervous system drugs (p = 0.001)." (PMID 36992840, 2023). "The patients in Group 1 had lower incidences of diabetes mellitus (DM), use of renin–angiotensin system blockers, statin, aspirin, clopidogrel, or ticlopidine, and MI or CHF than those in the other three groups." (PMID 37893212, 2023). "Vitamin D significantly reduced plasma renin in individuals with coronary artery disease and diabetes, according to two additional RCTs." (PMID 37968749, 2023). "Background/aim: Diabetes is a multifactorial syndrome that affects the functioning of the renin-angiotensin system (RAS)." (PMID 37637592, 2023). "In analogy to what was observed for renin, recessive INS mutations leading to early-onset diabetes are loss-of-function mutations." (PMID 37283036, 2023). "The current decisive algorithm of when to start ACE-inhibition and / or diuretics in children with diabetes or obesity relies on systolic and diastolic blood pressure and on renin blood levels." (PMID 36996194, 2023). "Eventually, only five of them met the criteria involved in the development of SVS, including beta blocking agents, drugs used in diabetes, agents acting on the renin-angiotensin system, diuretics, and calcium channel blockers." (PMID 37020515, 2023). "Vitamin D plays an important role in the occurrence of various cardiometabolic features, including diabetes, metabolic syndrome, renin-angiotensin system activation and inhibition of the production of some inflammatory factors." (PMID 37426181, 2023). "Plasma angiotensinogen prior to diabetes induction amounted to 706 ± 32 pmol·ml−1 and plasma renin and prorenin were 41 ± 2 and 507 ± 33 ng angiotensin I per ml·h−1, respectively (n = 47 for all)." (PMID 36106615, 2023). "Clinically, diabetes-induced activation of the renin-angiotensin axis is managed with antihypertensive medications." (PMID 36572735, 2022).